INS (insulin)
Diseases named in the same sentence as INS in open-access papers (continued):
Sharing a sentence is not in itself a finding about the gene and the disease.
Hypoglycemia (continued). "SGLT2 inhibitors function independently of insulin, thus posing a low risk of hypoglycemia." (PMID 39690416, 2024). "Consequently, future studies in pediatric patients are needed to elucidate the specific implications of SGLT2i in pediatric subgroups, such as those on insulin and at risk of hypoglycemia." (PMID 40302966, 2024). "Moreover, in human cardiac surgery, excessive insulin administration is the primary cause of postoperative hypoglycemia." (PMID 38393097, 2024). "However, the owner’s and pet’s quality of life can be negatively impacted, and the risk of hypoglycemia increases in parallel with more aggressive insulin treatments." (PMID 38539988, 2024). "This is due to several factors: therapeutic inertia, fear of hypoglycaemia and/or weight gain, poor communication, complexity of insulin titration, and the number of injections needed, with the associated reduced adherence to insulin therapy." (PMID 38679644, 2024). "Determining the cause of hypoglycemia partly relies on blood insulin and C-peptide assays." (PMID 39071705, 2024). "Physical activity is useful in maintaining blood glucose control and reducing insulin requirements but may be accompanied by an increased risk of hypoglycemia." (PMID 38541202, 2024). "These inconsistencies in results might be due to patients administering lower doses of Insulin or missing doses altogether out of concern for hypoglycemia, as our data reveals a notably higher occurrence of hypoglycemic episodes associated with Insulin use." (PMID 39570934, 2024). "Diminished hepatic insulin extraction may contribute to higher circulating insulin levels and hypoglycemia risk." (PMID 39555226, 2024). "Additionally, according to reports, fluoroquinolones cause hypoglycemia by stimulating the release of insulin from pancreatic beta cells by blocking K(ATP) channels and opening L-type voltage-dependent Ca(2+) channels." (PMID 38399785, 2024). "Indeed, compared with the wild-type mice, the TRPC1/4/5/6-deficient mice exhibited aggravated hypoglycemia at any time point analyzed until 60 min after the insulin administration." (PMID 39375537, 2024). "Historically, glucose lowering agents approved for management of T2D in patients with advanced CKD have been limited to insulin and sulfonylureas despite their associated risk of hypoglycemia and neutral effect on cardiovascular outcomes or progression of kidney disease." (PMID 39639039, 2024). "As such, any new insulin needs to be studiedcarefully to ascertain hypoglycemia risk." (PMID 38224978, 2024). "Furthermore, GLP-1 receptor (GLP-1R) agonists are widely used for treating Type 2 diabetes due to their ability to enhance glucose-dependent insulin secretion, reduce glucagon levels, and minimize the risk of hypoglycemia." (PMID 39582948, 2024). "Furthermore, alcohol consumption is known to worsen metabolic control, increase the risk of hypoglycemia, and disrupt patients’ capacity to manage their insulin therapy." (PMID 38791795, 2024). "However, insulin use in older people can bring additional hazards such as hypoglycaemia which can increase the risk of falls, cardiovascular morbidity, hospital admissions and mortality." (PMID 38778253, 2024). "As T-bet−/− mice are already known to be more insulin sensitive than WT mice, we wondered whether the antibiotic-induced weight loss might have resulted in lethal hypoglycaemia in this genotype." (PMID 39664730, 2024). "We did this because reduction of caloric intake increases the risk of hypoglycaemia in people using sulfonylurea derivatives or insulin (which were the first-choice second- and third-line (drug) treatments, respectively, in the Dutch guidelines at the time the study started)." (PMID 38546821, 2024). "It is suggested to avoid or reduce insulin dosage on HD day to minimize the risk of hypoglycemia." (PMID 39628691, 2024).
Hypoglycemia (continued). "The added benefits of weight loss, less insulin doses, daily injections, and hypoglycemia, accompanied by increased patients’ satisfaction related to therapy modifications, were maintained in the extension period in at least one-half of the randomized patients." (PMID 37787888, 2024). "However, such procedures are complicated by the risk of persistent hypoglycemia in 40% to 60% of patients, the need for pancreatic enzyme replacements, and inevitable progression to insulin-requiring diabetes." (PMID 37930757, 2024). "By carefully assessing the insulin dose and thoroughly assessing potential causes of hypoglycemia, such as suboptimal timing or the site of insulin administration, renal and hepatic dysfunction, hypothyroidism, weight loss, and nutrition status, optimal glycemic control can be achieved." (PMID 38541119, 2024). "Although GLP-1 RAs by themselves have a low risk of hypoglycemia, when used in combination with sulfonylureas and/or insulin, some experts recommend lowering the dose of sulfonylureas and short-acting and low-acting pancreatic islet analogs before or during the use of GLP-1 RAs." (PMID 39040467, 2024). "Still, the risk of hypoglycemia is lower when compared with insulin and sulfonylureas." (PMID 38243951, 2024). "Urinary microalbumin above the normal level suggests that patients may have an early renal injury, which affects the excretion of insulin, leading to insulin accumulation in the patient’s body and susceptibility to hypoglycemia." (PMID 39610841, 2024). "In addition, it has been shown that enhanced secretion of vasopressin during insulin-induced hypoglycemia is associated with elevated release of ACTH." (PMID 39769071, 2024). "Intensive insulin therapy, involving multiple daily injections or continuous subcutaneous insulin infusion, has proven effective in reducing microvascular complications but poses a higher risk of severe hypoglycemia." (PMID 39065795, 2024). "Interestingly, the presence of islet delta-cells is critical for normal glycaemic control, as ablation of delta-cells in mice was shown to cause a hypersecretion of insulin, resulting in hypoglycaemia and death." (PMID 38612880, 2024). "However, when applying this regimen, strict monitoring and anticipated precautions should be retained, notably regarding the risk of weight gain, hypoglycemia, and the other adverse events of insulin therapy." (PMID 38213906, 2024). "Additionally, while SGLT2Is and GLP1As have positive cardiovascular and renal effects, insulin has a neutral effect in this respect, but has a high risk of hypoglycemia and weight gain." (PMID 38658983, 2024). "However, insulin therapy has limitations in achieving optimal glycemic control, and the risk of hypoglycemia remains a significant barrier to achieving tight glycemic control." (PMID 38097717, 2024). "However, the most notable advantage of IDeg was its lower risk of hypoglycemia, particularly nocturnal hypoglycemia, which is a significant concern in insulin therapy." (PMID 39766270, 2024). "Therefore, insulin, sulphonylurea secretogogues, glinide secretogogues, and other glucose‐lowering medications at high risk of hypoglycemia should be used with caution." (PMID 38571669, 2024). "This may cause insulin accumulation, increased insulin doses, and a risk of hypoglycemia simultaneously." (PMID 38698018, 2024). "Sulfonylureas are insulin secretagogues that are generally metabolized by the liver and may cause hypoglycemia." (PMID 39149651, 2024). "GLP-1-RAs differ from sulfonylureas and insulin because they may aid in weight loss and have a low risk of hypoglycemia." (PMID 39355484, 2024). "We also found that in studies reporting lipohypertrophy measured by ultrasonography, the association with unexplained hypoglycemia, HbA1c values, and total daily insulin dose was more substantial than in those with only clinical assessment of lipohypertrophy (P < 0.05)." (PMID 38215209, 2024).
Hypoglycemia (continued). "Intensive insulin therapy carries a risk of hypoglycemia during treatment of hyperglycemic crises." (PMID 38594758, 2024). "In this regard, the combination of basal insulin (BI) and GLP-1 RA has potent glucose lowering actions and is associated with less weight gain and hypoglycemia compared with fully intensified insulin regimens, thus representing a valid alternative to multiple daily injections of insulin." (PMID 38767675, 2024). "Similarly, hypoglycemia frequently associated with insulin treatment can cause irreversible structural brain abnormalities." (PMID 37511061, 2023). "Hypoglycemia is caused by injecting too much insulin, which can be life-threatening." (PMID 38111457, 2023). "Improving adjustments on food intake and insulin therapy with exercise may decrease the risk of hypoglycemia after exercise." (PMID 36964201, 2023). "The automated suspension of insulin delivery decreases the risk of hypoglycaemia and might offer a sense of safety that extends beyond its impact on the occurrence of hypoglycaemia episodes." (PMID 37593226, 2023). "In addition, subcutaneous insulin injection can lead to peripheral hyperinsulinemia and a high risk of hypoglycemia." (PMID 37485249, 2023). "With regard to the effects on the central nervous system, pathological studies on material from patients with hypoglycemia (caused either by exogenous insulin, hypoglycemic medication or insulinoma) demonstrate that neurons in the neocortex, hippocampus, thalamus, and hypothalamus are affected most." (PMID 37308982, 2023). "However, insulin dosage can be reduced and glycemic stability improved, minimizing the risk of hypoglycemia." (PMID 36981876, 2023). "Patients treated with insulin may initiate tirzepatide therapy and carefully reduce the insulin dose to minimize the risk of hypoglycemia." (PMID 36767008, 2023). "When patients who received insulin or secretagogues were selected (n = 303), the association between hypoglycemia (which could be considered as secondary to hypoglycemic treatment) and mortality during hospitalization was also maintained (P = 0.007)." (PMID 38044455, 2023). "On the other hand, it has yet to be established whether insulin-independent mechanism(s) related to fasting can also increase susceptibility to hypoglycemia." (PMID 37166980, 2023). "The impact that these cyclic changes may have on blood glucose levels and insulin needs and the consequent risk of hypoglycemia during or after exercise are still unknown in this population." (PMID 36833469, 2023). "For insulin-treated patients with HU, they are advised to raise their glycemic targets to strictly avoid hypoglycemia for at least several weeks in order to partially reverse hypoglycemia unawareness and reduce the risk of future episodes." (PMID 37964960, 2023). "Hypoglycemia has multiple causes, but the most common is a complication of insulin treatment." (PMID 37823058, 2023). "Eventually, most patients require treatment intensification and progress into complex drug regimens with multiple daily injections, including insulin therapy, which leads to more risk associated with hypoglycemia, hypoglycemia associated falls and neurological deficits." (PMID 37088807, 2023). "In addition, the duration and intensity of PA and 2-hour bolus insulin were weakly associated with hypoglycemia for walking, running, and cycling." (PMID 37274763, 2023). "Pioglitazone might be appropriate for elderly DM patients because of its insulin-sensitizing effect and low risk of hypoglycemia." (PMID 37036483, 2023). "In T1D and late-stage (insulin deficient) T2D, the relationship between glucagon secretion and blood glucose levels is inverted, such that plasma glucagon levels rise after a mixed-meal and fall during hypoglycemia." (PMID 38298268, 2023).
Hypoglycemia (continued). "In the trial by Ferguson and the HypoAna and HypoDeg trials, insulin doses were adjusted individually according to baseline HbA1c to avoid imposing further hypoglycemia risk on the participants by applying a titration regimen while also resembling everyday clinical practice more." (PMID 38089060, 2023). "However, studies comparing the effects of different insulin regimens in people at increased risk of hypoglycemia must be carefully designed." (PMID 38089060, 2023). "In the present study, having a school assistant who takes care of or reminds the child of regular blood glucose monitoring, carbohydrate assessing, insulin dosing and measures to prevent hypoglycaemia was strongly associated with optimal metabolic control (both HbA1c and TIR)." (PMID 37749959, 2023). "Non-insulin therapies, due to the low risk of hypoglycemia concurrently with the multifactorial CV protective effects, may be proved to be the best treatment option in the future." (PMID 38004366, 2023). "Considering some medications, such as insulin, sulfonylurea, and anti-depressants are known to be associated with hypoglycemia, we investigated the prescription record of selected patients, which found a significant lower exposure of all these medication in the hypoglycemic group." (PMID 37700268, 2023). "Moreover, myoinositol supplementation reduces the risk of insulin need, preeclampsia or gestational hypertension, preterm birth, and neonatal hypoglycemia." (PMID 37836508, 2023). "AD may cause a decrease in insulin need with hypoglycemia, as well as a thyrotropin (TSH) increase due to the absence of glucocorticoid-transmitted inhibition of TSH secretion." (PMID 36980146, 2023). "The hypoglycemic action of curcumin, mainly attributable to increased glucose uptake by cells, and the augmented secretion of insulin might have exacerbated the hypersecretion of the hormone caused by insulinoma and possibly led to hypoglycemia." (PMID 37047589, 2023). "Sulphonylureas and insulin, however, have been shown to increase the risk of hypoglycaemia." (PMID 36662823, 2023). "Hypoglycemia is the most common adverse event associated with insulin therapy." (PMID 37120562, 2023). "A combination of insulin and oral medication can have more comprehensive benefits, such as increasing the effect of peripheral insulin, reducing insulin dosage, reducing the risk of hypoglycemia, improving blood glucose control, and reducing weight gain." (PMID 38027146, 2023). "Finally, the risk of hypoglycemia should be avoided, especially when therapy is implemented and insulin therapy is started." (PMID 38068310, 2023). "Indeed, the risk of hypoglycemia induced by insulin can result in acute glycemic variability and impose a harmful impact on prognosis." (PMID 36896774, 2023). "However, the availability of insulin analogs has improved the effectiveness of insulin therapy in addition to minimizing the risk of associated hypoglycemia." (PMID 36650625, 2023). "This may be explained by either the effect of hypoglycaemia to lower mean blood glucose or a protective effect against hypoglycaemia due to greater insulin resistance associated with higher HbA1c." (PMID 37439960, 2023). "Looking at the broad categories of risks for hypoglycemia, exercise is known to consume glycogen stores, increase insulin sensitivity, and has been shown at moderate intensity to blunt autonomic response to hypoglycemia, all three of which increase the risk for hypoglycemia." (PMID 37274763, 2023). "However, treatment with GLP-1 RA and DPP-4 inhibitors in hospitalized patients has been associated with similar glycemic control and lower rates of hypoglycemia compared with insulin regimens." (PMID 36964858, 2023). "Moreover, metformin displayed superiority to insulin in reducing the risk of hypertensive disorders in pregnancy, hyperbilirubinaemia, neonatal hypoglycaemia and NICU admission." (PMID 37072764, 2023).
Hypoglycemia (continued). "Thus, while better glucose regulation is needed to reduce the risk of both micro- and macrovascular complications, the risk of hypoglycaemia remains a limiting factor in insulin-dependent patients." (PMID 36404376, 2023). "Moreover, eGFR less than 60 mL/min/1.73 m2, history of previous severe hypoglycemia events, and insulin use were associated with increased risk of severe hypoglycemia." (PMID 37758787, 2023). "Hypoglycemia in DS may be attributed to an accelerated fasting state secondary to insulin resistance, scarce stores of glycogen, and deficient gluconeogenesis." (PMID 40041273, 2023). "Importantly, however, insulin exposure and, consequently, the risk of hypoglycaemia are greatest during the first dosing interval after a higher-than-normal dose." (PMID 37308751, 2023). "However, insulin therapy intensification imposes the increased risk of hypoglycemia especially in toddlers and preschool children." (PMID 36800034, 2023). "Depending on the type of insulin and the timing of administration, this adjustment could increase the risk of hypoglycemia both during and after exercise due to higher levels of insulin in circulation during exercise." (PMID 36833469, 2023). "Hypoglycemia in this setting was potentially caused by increased insulin dissociation from the insulin-antibody complex due to low affinity or decreased glucose counter-regulation and prolonged free insulin half-life, while other mechanisms warrant further investigation." (PMID 37143729, 2023). "However, premixed insulin is prone to causing hypoglycemia, which leads to weight gain and poor control of postprandial blood glucose levels." (PMID 38027146, 2023). "After adding basal insulin to CVII therapy, the daily insulin dose decreased, and glycemic control further improved with an acceptable hypoglycemia risk, indicating that timely and adequate basal insulin replacement was important during the postoperative parenteral period after TP." (PMID 36860372, 2023). "Insulin pump therapy is associated with improved glycaemic control and reduced hypoglycaemia compared with multiple daily insulin injections, and CGM is associated with improved glucose control and reduced hypoglycaemia compared to fingerstick capillary glucose monitoring." (PMID 37289734, 2023). "Reducing the basal insulin dose could mitigate this risk, but fasting might also predispose to hypoglycemia by impairing insulin-independent mechanism(s), such as CRRs." (PMID 37166980, 2023). "However, this necessary intensification of insulin therapy is often associated with a decrease in quality of life and an increase in treatment costs, and the risk of hypoglycemia." (PMID 37736430, 2023). "Additionally, the lag time associated with CGM readings in the presence of prandial insulin and exercise must be acknowledged when educating on the risks of hypoglycaemia." (PMID 40303277, 2023). "It produces insulin and causes severe hypoglycemia with neuroglycopenic symptoms." (PMID 37629713, 2023). "In our study, 17% of hypoglycaemia occurred during the most vulnerable nocturnal period (between 00:00 and 06:00), which is less than is expected in higher risk patients, e.g., type 1 or advanced insulin-dependent type 2 diabetes patients." (PMID 36882852, 2023). "However, patients at high risk for hypoglycaemia were excluded from participation and participants injected their long-acting insulin in the morning." (PMID 36879098, 2023). "Reducing the basal insulin after exercise reduces the risk of late hypoglycemia." (PMID 36964201, 2023). "The results showed that the course of disease, BMI, fasting C-peptide and creatinine were independent risk factors for hypoglycemia after intensive insulin therapy (P<0.05), while instantaneous scanning glucose test system monitoring and glucometer monitoring were protective factors (P<0.05)." (PMID 38223574, 2023).